CENATAC-AS1 (CENATAC antisense RNA 1)
Synonyms: AP003392.1
Gene: Long non-coding RNA gene on chromosome 11 (119,003,742 to 119,004,893, reverse strand). Ensembl gene ENSG00000254428.
Diseases named in the same sentence as CENATAC-AS1 in open-access papers:
CENATAC-AS1 is named in the same sentence as 1 disease in open-access papers, as found by Europe PMC text mining. Sharing a sentence is not in itself a finding about the gene and the disease.
CENATAC-AS1 shares sentences with these, for which no sentence is quoted: gastric cancer (1 paper).